ENSG00000288894 (novel protein)
Gene: Protein-coding gene on chromosome 17 (63,550,603 to 63,608,347, forward strand). Ensembl gene ENSG00000288894.
Genetic constraint (gnomAD): Missense variants: 128 observed, 456.39 expected, observed/expected ratio (o/e) 0.28, 90% interval 0.24 to 0.32. Synonymous variants: 143 observed, 172.07 expected, observed/expected ratio (o/e) 0.83, 90% interval 0.73 to 0.95.